LGALS3 (galectin 3)
Diseases named in the same sentence as LGALS3 in open-access papers (continued):
Sharing a sentence is not in itself a finding about the gene and the disease.
thyroid cancer (continued). "We show here the possibility to obtain thyroid cancer imaging in vivo by targeting galectin-3." (PMID 19020658, 2008). "Anyway it should be stressed that LNAB and cell-block technique can eventually provide optimal substrates for comparative immunohisto-cytochemistry (on seriate tissue sections) directed to evaluate the expression of galectin-3 and other potential markers of thyroid cancer." (PMID 16804521, 2006). "Detection of both galectin-3-positive atypical areas and microcarcinomas, in a subset of HTs, supports the hypothesis that precursor lesions of thyroid cancer may be present in these thyroid conditions." (PMID 15292926, 2004). "Furthermore, galectin-3 (Gal-3), a beta-galactoside binding protein, is involved in several biological functions and its expression increased in different types of cancer such as thyroid cancer." (PMID 35203561, 2022). "However, strategies to target galectin-3 for thyroid cancer therapy are less well studied." (PMID 34035807, 2021). "Besides, Galectin-3 expression in thyroid carcinoma has been linked with aggressive clinical features whilst negative Galectin-3 carcinomas seem to present a slightly more favorable course with fewer lymph node metastases." (PMID 26186733, 2015). "As was found in this study, galectin-3 is expressed in normal thyroid and the higher levels in thyroid cancers, as seen in the present study, may be used to separate benign and malignant thyroid tissues provided appropriate evidence-based data are taken into consideration." (PMID 22039439, 2011). "Galectin-3 is significantly overexpressed in thyroid cancer, especially in PTC, one of the most frequent kinds of thyroid cancer." (PMID 38501105, 2024). "Even galectin-3 and HBME-1 are generally expressed in high proportions, but they are less specific for PTC as they have been found in several subtypes of thyroid cancer." (PMID 38137593, 2023). "A positive correlation between galectin-3 and CD74 expression was noted in thyroid cancer (unpublished observation)." (PMID 34035807, 2021). "Four candidate proteins, galectin-3, NAG-1, TIMP-1, and osteoprotegerin (OPG), were identified as potential biomarkers of thyroid cancer." (PMID 34208730, 2021). "Some proteins' alteration was found in thyroid cancer, such as CK19, TG, Ki67, Calcitonin, TTF-1, BRAF, RET, HBME-1, SERPINA1, TfR1/CD71, FHL1 and galectin-3." (PMID 22188859, 2011). "HBME-1, galectin-3 and CK19 were the markers most frequently referred to in literature and most commonly used for differentiating benign from malignant thyroid tumours." (PMID 19321014, 2009). "Galectin-3 immunostaining allows to distinguish the thyroid carcinoma cells that appear colored in brown from the normal thyroid cells that are Galectin-3 negative at immunostaining." (PMID 39685748, 2024). "Galectin-3, a carbohydrate-binding protein involved in tumor progression and metastasis, has also been investigated as a PTC tissue marker due to its specificity in the differential diagnosis of thyroid cancer." (PMID 37547301, 2023). "All CNB samples were stained by immunohistochemistry (IHC) using antibodies against CK19, galectin-3, HBME-1, and CD56 and detected by next-generation sequencing (NGS) using an OncoAim® thyroid cancer multigene assay kit (Singlera Genomics) that detected 26 genes." (PMID 34308507, 2021). "Recently, a galectin-3-based immuno-positron emission tomography (immuno-PET) for imaging thyroid cancer in vivo has been developed and used in preclinical experimental models of thyroid cancer xenografts." (PMID 29393868, 2018). "In recent years, several immunohistochemical markers, such as cytokeratin-19, galectin-3, HBME-1, fibronectin-1, and intracellular sodium/iodide symporter, or their combinations have been used to differentiate benign thyroid diseases from thyroid cancer." (PMID 27446209, 2016).
thyroid cancer (continued). "In a previous pilot study we demonstrated that six recently identified marker genes (ADM3/HGD1/LGALS3/PLAB/TFF3/TG) can be successfully applied for a molecular discrimination of benign and malignant thyroid tumours including follicular thyroid neoplasia using surgically removed tissue samples." (PMID 22223087, 2012). "Moreover we recently demonstrated that galectin-3 immunotargeting represents an useful diagnostic tool for identifying preoperatively malignant thyroid proliferations on immuno-cytological bases, although some thyroid carcinomas (about 10–15% depending by the studies) do not express galectin-3." (PMID 19020658, 2008). "In addition to galectin-3, other markers such as Hector Battifora mesothelial cell-1 (HBME-1), cytokeratin-19 (CK19), and cluster differentiation antigen 56 (CD56) can facilitate the diagnosis of thyroid carcinoma in both histologic and cytologic preparations." (PMID 37324272, 2023). "GB1107 and TD139 did not change the expression of galectin-3 in thyroid cancer cells." (PMID 34035807, 2021). "Collectively, the responses to galectin-3 inhibitors were different in nonmalignant follicular epithelial cells compared to thyroid cancer cells, and the difference may result from differential expression of galectin-3." (PMID 34035807, 2021). "Galectin-3 is strongly expressed in thyroid carcinoma cells, but not in benign tumors, and as such, it is associated with the levels of GTP-bound K-Ras, thus contributing to thyroid carcinoma malignancy." (PMID 27242966, 2016). "However, most recent investigations in this area did not confirm these findings and support usefulness of galectin-3 as biomarker for thyroid cancer." (PMID 23658855, 2010). "Among 85 cases tested, 14 galectin-3-positive cases were discovered preoperatively (11 thyroid cancers and three adenomas confirmed at the final histology), whereas galectin-3-negative cases were 71 (one carcinoma and 70 benign proliferations at the final histology)." (PMID 16804521, 2006). "Interestingly, among the 12 thyroid carcinomas detected at the final histology, only one did not express galectin-3." (PMID 16804521, 2006). "It is reported that well-differentiated thyroid carcinomas almost invariably express galectin-3 and galectin-7, while benign thyroid proliferations do not, so expression of galectin-3 and galectin-7 in thyroid malignancy may be as potential diagnostic indicators." (PMID 29951528, 2018). "In addition, although the expression of LGALS3 did not differentiate the BEN group from any of the MAL subgroups, it may distinguish the MALpapillary from the MALfollicular subtype of thyroid cancer." (PMID 30781659, 2019).
pulmonary fibrosis (87 papers, 2013 to 2026). Chronic progressive interstitial lung disorder characterized by the replacement of the lung tissue by connective tissue, leading to progressive dyspnea, respiratory failure, or right heart failure. "In murine models of pulmonary fibrosis, loss of galectin-3 is protective, with galectin-3−/− mice demonstrating decreased collagen staining and lower total lung collagen compared with WT mice." (PMID 38641066, 2024). "Galectin-3 also plays a key role in pulmonary-associated lung fibrosis in COVID-19, with positive correlations found between Gal-3 and various markers of inflammation, endothelial injury, and tissue injury." (PMID 37298569, 2023). "Further studies are planned to confirm the preliminary results and to verify possible associations of galectin-3 with long-term consequences of COVID-19, including pulmonary fibrosis." (PMID 34439802, 2021). "Further studies are planned to confirm our preliminary findings and to verify the possible associations of galectin-3 with long-term consequences of COVID-19, including pulmonary fibrosis." (PMID 34439802, 2021). "Galectin-3 (Gal-3) has been implicated in the development of pulmonary fibrosis." (PMID 36552035, 2022). "Furthermore, bleomycin-induced lung fibrosis in Galectin-3—deficient mice was significantly diminished due to reduced transforming growth factor (TGF)-β regulated myofibroblast activation and production of collagen." (PMID 32455781, 2020). "Galectin-3 (Gal-3), a fibrosis-related biomarker involved in macrophage activation and matrix remodeling, has been linked to faster lung function decline, radiographic fibrosis progression, and increased mortality in systemic sclerosis-associated pulmonary fibrosis." (PMID 41010963, 2025). "The pharmacological inhibitors of Galectin-3 have demonstrated efficacy in treating various diseases, including nonalcoholic steatohepatitis and pulmonary fibrosis in animal models, and even in humans." (PMID 41477833, 2026). "3′-bis-(4-aryltriazol-1-yl) thiodigalactoside (GB039, formerly named TD139), a synthetic small molecule that antagonizes LGALS3 activity by binding to the carbohydrate recognition domain, was effective in idiopathic pulmonary fibrosis and retinal degeneration." (PMID 41145409, 2025). "In a silica-induced pulmonary fibrosis, galectin-3 (LGALS3) markedly promotes endothelial-to-mesenchymal transition (EndMT) through activation of the PI3K/AKT signaling pathway." (PMID 40988754, 2025). "Recent advances in the development of galectin-3 inhibitors for other conditions, such as idiopathic pulmonary fibrosis and cardiovascular diseases, provide a rationale for investigating their application in PCOS management." (PMID 39958874, 2024). "Galectin-3 is a cytoplasmatic b-galactoside-binding lectin identified in systemic fibroproliferative conditions, such as systemic sclerosis and pulmonary fibrosis." (PMID 38433835, 2024). "Gal-3 inhibition by TD139, a high-affinity galectin-3 inhibitor, attenuates β-catenin activation and reduces fibrosis in an animal model of bleomycin-induced lung fibrosis." (PMID 39125698, 2024). "Galectin-3 is a beta-galactoside-binding lectin involved in inflammation and lung fibrosis and postulated to enhance thrombosis." (PMID 37175392, 2023). "More specifically, the role of galectin-3 as a mediator of pulmonary fibrosis has drawn attention since the inhibition of galectin-3 was found to decrease bleomycin-induced fibrosis and lung inflammation in mice." (PMID 37958814, 2023). "TD-139, a galectin-3 inhibitor, has been already available as a treatment for idiopathic pulmonary fibrosis (IPF)." (PMID 37628961, 2023). "While the consequences of infection-related elevation of galectin-3 levels remain to be fully understood, galectin-3 upregulation enhanced inflammatory cytokine levels and myofibroblast activation, both with roles in lung fibrosis." (PMID 37238973, 2023).
pulmonary fibrosis (continued). "Along these lines, galectin-3 contributes to pulmonary fibrosis, which is a relatively common and very serious complication of COVID-19 disease." (PMID 37238973, 2023). "TD139, a 3,3’-bis-(4-aryltriazol-1-yl) thiodigalactoside has been considered as the most advanced small-molecule galectin-3 inhibitor and is now in clinical trials for idiopathic pulmonary fibrosis (IPF)." (PMID 36115971, 2022). "Further studies reported that galectin-3 induces pulmonary fibrosis by promoting the activity of the transforming growth factor β (TGF-β)." (PMID 35806317, 2022). "TD139, a thiodigalactoside derivate with high binding affinity for the galectin-3 carbohydrate recognition domain, has previously shown efficacy in murine models of lung fibrosis and corneal neovascularization." (PMID 36115971, 2022). "Galectin-3 is known to play a role in the pathogenesis of pulmonary fibrosis, and clinical trials testing galectin-3 inhibitors are currently underway for the treatment of idiopathic pulmonary fibrosis." (PMID 35115644, 2022). "The Galectin-3 protein is linked to COVID-19 pathogenesis in particular in terms of its role in Cytokine Storm Syndrome (CSS) and as a mediator of lung fibrosis." (PMID 34572394, 2021). "To further investigate if the role of galectin-3 in BLM-induced pulmonary fibrosis is related to EC activation and EndMT, we first used human lung micro-endothelial cells (HPMECs) to induce EndMT." (PMID 33771973, 2021). "Along the time axis of pulmonary fibrosis, the expression trends of C3ar1 and Lgals3 were highly consistent with the results of pseudo-temporal analysis." (PMID 33771973, 2021). "Inhibiting the expression of galectin-3 showed a stronger effect against the development of pulmonary fibrosis than inhibiting C3ar1." (PMID 33771973, 2021). "Galectin-3 (Gal-3) is a pro-fibrotic, mammalian ß-galactoside binding lectin found to be highly upregulated in the injured lung, particularly in patients with idiopathic pulmonary fibrosis (IPF) suffering acute exacerbations." (PMID 34526900, 2021). "At the same time, we intraperitoneally injected the mice with the C3ar1 antagonist SB290157 or the galectin-3 antagonist GB1107 during the development of BLM-induced pulmonary fibrosis." (PMID 33771973, 2021). "Another antifibrotic effect of use of the Galectin-3 inhibitors was shown in murine model of lung fibrosis induced by bleomycin." (PMID 32455781, 2020). "FN-1 and LGALS3 are known to participate in pulmonary fibrosis and be produced by fibroblasts and endothelial cells, and now by human HPM cells." (PMID 27459687, 2016). "Moreover, level of galectin 3 (GAL3), is increased in patients of pulmonary sarcoidosis and fibrosis and targeting GAL3 by small molecule inhibitors was showed efficacious in mouse models of bleomycin-induced lung fibrosis." (PMID 38550597, 2024). "Overall, given the role of galectin-3 in immunomodulation and inflammatory response, this protein may represent a prominent pharmacological target for lung fibrosis in COVID-19 patients." (PMID 37958814, 2023). "Indeed, diverse galectin-3 inhibitors have been reported to counteract fibrotic disorders, including idiopathic pulmonary fibrosis." (PMID 35806317, 2022). "Our current findings also suggest that galectin-3 is a biomarker of pulmonary fibrosis in SSc." (PMID 35042522, 2022). "Interestingly, the putative Gal-3BP/galectin-3 profibrotic mechanism of action resembles those mediated by SARS-CoV-2 in the induction of the detrimental outcome of pulmonary fibrosis, thought to be related to TGF-β increased levels." (PMID 35806317, 2022). "Notably, we were able to observe that ECs widely express galectin-3 protein (co-labeled) in the BLM-induced pulmonary fibrosis group (BLM + DMSO), which corroborates the results of the single-cell analysis." (PMID 33771973, 2021). "Hence, it stands to reason that galectin-3 plays more vital roles in BLM-induced pulmonary fibrosis." (PMID 33771973, 2021).
pulmonary fibrosis (continued). "Inhibition of galectin-3 mitigates bleomycin-induced pulmonary fibrosis in mouse models; and therefore, it could be an effective therapeutic target in these disorders." (PMID 33923064, 2021). "Galectin 3 is a carbohydrate-binding protein expressed by macrophages, epithelial cells, and alveolar cells, which drives macrophage-related hyper-inflammation, mediates viral adhesion, and promotes lung fibrosis." (PMID 33673529, 2021). "Galectin-3 (Gal-3), a member of the lectins family, which bind to β-galactoside, has been reported to be involved in regulating many conditions, including HF, hepatic and pulmonary fibrosis." (PMID 33934700, 2021). "Additionally, there is evidence that the activity of the TGF-β receptor in lung fibrosis is dependent on galectin-3 protein and that inhibition of galectin-3 is inhibits receptor activity." (PMID 24130706, 2013). "A statistically (p = 0.043) and biologically (10.2%) significant increase in galectin-3 occurred only in ILD, likely reflecting pulmonary fibrosis more strongly." (PMID 41010963, 2025). "The galectin-3 inhibitor GB0139, which targets idiopathic pulmonary fibrosis, is also in clinical phase IIb (ClinicTrials.gov Identifier: NCT03832946)." (PMID 39194690, 2024). "Recently, inhibitors of TGFβ (1D11), PDGF (Nintedanib), AKT (triciribine), galectin-3 (TD139), LPA-1 (AM966), and LOXL2 (AB0023) have shown promising and beneficial effects in rodent models of lung fibrosis." (PMID 38534359, 2024). "In contrast to the control mice, mice with pulmonary fibrosis exhibited notably higher levels of lung proteins such as TGF-βR2, SKP-1, CHI3L1, OGG1, and Galectin-3, alongside lower expression of p-4Ebp1, SARA, p-P70S6K, and PP2A." (PMID 38259493, 2023). "With pulmonary fibrosis in ARDS representing a life-threating outcome of SARS-CoV-2 infection and serum galectin-3 levels predicting survival in ARDS, galectin-3 levels were also measured in COVID-19 patients." (PMID 37238973, 2023). "In particular, Galectin-1 (Gal-1) and Galectin-3 (Gal-3) act as regulators of inflammatory response in lung diseases such as COPD and idiopathic pulmonary fibrosis (IPF), making them good targets for drug design therapies." (PMID 37050230, 2023). "Galectin-3-knockout BLM-treated mice showed significant changes in fibrosis progression due to a reduction in their lung collagen level and subsequent lung fibrosis." (PMID 35268581, 2022). "The expression of TGF-β receptors on the cell surface of amniotic epithelial cells is regulated by galectin-3, and β-galactoside-binding lectin also influences TGF-β-induced lung fibrosis." (PMID 35268581, 2022). "In a mouse model, TGF-β and bleomycin-induced lung fibrosis was blocked by TD139, a galectin-3 small molecule inhibitor with an affinity for carbohydrate-binding domain via inhibiting β-catenin nuclear translocation." (PMID 36272642, 2022). "The detection of LGALS3 is important because this protein is profibrotic and concentrations are significantly higher in HPS-1 pulmonary fibrosis and correlate with disease severity." (PMID 27459687, 2016). "Conversely, SSc-ILD patients showed a 6.08% annual reduction in lung volume (already low at baseline), lower CT densitometry values across slices, and an increase in galectin-3—suggestive of progressive pulmonary fibrosis rather than renal involvement." (PMID 41010963, 2025). "scRNA-seq revealed that genes complement C3a receptor 1 (C3ar1) and galectin-3, which play a key role in EC dynamic transition, were ubiquitously expressed by ECs in BLM-induced lung fibrosis, and ECM deposition was reduced and lung fibrosis was relieved after inhibition of this gene expression." (PMID 36825939, 2023). "Notably, galectin-3 is considered a pro-fibrotic molecule, elevated in the plasma and broncho-alveolar lavage fluid (BALF) of patients with idiopathic pulmonary fibrosis (IPF)." (PMID 37958814, 2023).
pulmonary fibrosis (continued). "Interestingly, they all have the inhibition of Galectin 3 as target in two different clinical fibrosis settings, namely non-alcoholic steatohepatitis (NASH) with advance fibrosis and idiopathic pulmonary fibrosis (IPS)." (PMID 35897786, 2022). "Therefore, it stands to reason that GB1107 inhibited galectin-3 expression and attenuated the development of BLM-induced pulmonary fibrosis by suppressing the AKT/GSK3β/β-catenin singling pathway." (PMID 33771973, 2021). "Galectin-3 inhibitor, TD139, also impaired progression of lung fibrosis." (PMID 32455781, 2020).